LEP (leptin)
Diseases named in the same sentence as LEP in open-access papers (continued):
Sharing a sentence is not in itself a finding about the gene and the disease.
metabolic disorders (continued). "Overweight adolescent girls with PCOS and metabolic disorders (MD+/OW) showed higher CRP, leptin, and a two-fold increase in IL-6 and IL-18 concentrations compared to the control group of healthy girls (p < 0.05 for all parameters)." (PMID 32397375, 2020). "However, further studies are required because associations between leptin and metabolic disorders are rather complex and non-linear, and might be gender specific." (PMID 32570840, 2020). "Augmented plasma leptin induced by HFD consumption were significantly reduced after SA treatment, suggesting a potential benefits of SA in other metabolic diseases." (PMID 32218700, 2020). "Furthermore, because leptin plays a key role in regulating developmental programming, we examined the leptin levels in mammary tissue and different milk samples in order to link maternal DE exposure to a potential for subsequent risks of growth and metabolic disorders in their offspring." (PMID 30763367, 2019). "Leptin (gene: LEP), adiponectin (gene: ADIPOQ), and resistin (gene: RETN) are candidate adipokines for investigation of metabolic diseases, as all three are involved in regulation of metabolism, appetite, and insulin sensitivity." (PMID 28413567, 2017). "Neuron-specific restoration of SH2B1β not only corrected the metabolic disorders in mice, but also improved JAK2-mediated leptin signaling and leptin regulation of orexigenic neuropeptide expression in the hypothalamus." (PMID 22474595, 2012). "Next, we substituted individual measurements of leptin and ADIPOQ with their ratio based on compelling evidence that this ratio serves as a promising biomarker not only for metabolic disorders and low-grade inflammation but also for assessing endometrial receptivity." (PMID 41300953, 2025). "Moreover, in obese individuals, visceral adipose expansion leads to the release of high levels of leptin, resistin, TNF-α, and IL-6, and low levels of adiponectin, which promote inflammation and metabolic disorders." (PMID 40095937, 2025). "The link between metabolic disorders and fibrotic diseases, like FS, may thus be mediated, in part, by the SOCS3-induced blockade of both leptin and insulin pathways, perpetuating chronic inflammation and tissue fibrosis." (PMID 40095902, 2025). "In particular, leptin accumulates to a larger extent than adiponectin in CKD, and this highly abnormal ratio may favor the onset of IR and metabolic disorders." (PMID 32290535, 2020). "Moreover, based on preclinical studies, certain cytokines (FGF21, leptin, adiponectin, irisin) that can induce improvements in glucose and lipid metabolism and may emerge as novel targets of broader and more efficacious treatments and prevention of metabolic disease." (PMID 31736870, 2019). "Given the disease-related changes in levels of relevant cytokines (for instance, leptin, adiponectin, reisitin, FGF21, Fetuin A, TNF-α, IL-6, MCP-1), these factors may serve as biomarkers for the early detection of metabolic disorders." (PMID 31736870, 2019). "Offspring clinical markers of metabolic disease correlated positively with leptin plasma levels and gene expression but not with average LEP DNA methylation." (PMID 28413567, 2017). "In contrast, for young men, eGFR based on creatinine and evaluation of visceral fat level and leptin may offer more relevant insights, even in the absence of overt metabolic disease." (PMID 41200622, 2025). "In addition, other bioactive factors, such as leptin, adiponectin, tumor necrosis factor-α, interleukin-6, interleukin-8, and MCP-1, can also be released from perirenal fat, which is involved in the pathogenesis of CVD, metabolic disorders, and T2DM." (PMID 35370949, 2022). "To determine whether the upregulation of Fetuin B and leptin can persist during the progression of metabolic disorders by feeding the HFD for a longer period, we further measured body fat, FBG levels and serum leptin and Fetuin B levels in mice fed HFD or chow for 18 weeks." (PMID 35896788, 2022).
metabolic disorders (continued). "The beneficial effects of CTRP1 are related to modulation of the activity of AMPK, AKT, and upregulation of leptin, suggesting CTRP1 may serve as a target in treating metabolic diseases, as well as the potential use of CTRP1 by gene transfer for the treatment of metabolic diseases." (PMID 36195912, 2022). "In addition, we and others have previously reported that fetal leptin gene expression and protein levels might be regulated by LEP promoter DNAm adaptations to maternal glycemic variations and other metabolic disorders during pregnancy." (PMID 31947745, 2020). "However, neither hs-CRP nor ghrelin, leptin or cystatin C correlated with metabolic disease remission after surgery in either group." (PMID 33208757, 2020). "Moreover, even though we did not detect significant changes in circulating LEPTIN and ADIPONECTIN, we found significant decrease in ADIPSIN, another adipokine, linked to increased fat mass and adipose tissue dysfunction in metabolic disorders, at 6M of T therapy." (PMID 39286266, 2024). "Although leptin and related metabolic markers were not included, nor were a systematic assessment of weight and/or the existence of metabolic disease performed, some of the measured cytokines and chemokines have been noted in the context of metabolic diseases and depression." (PMID 31554241, 2019). "However, in women with AO with and without MetS/metabolic disorders (general cohort), carriers of the 223R allele of the LEPR gene, leptin levels were higher than those in individuals with the Q223Q genotype (57.124 ± 0.370 ng/mL and 46.301 ± 2.752 ng/mL, resp.; p = 0.030)." (PMID 26504811, 2015). "The group (MD+/OW) was also characterized with higher levels of CRP, leptin, MDA, IL-18, MIF (p < 0.05), when compared to overweight patients with PCOS in the absence of metabolic disorders (MD−/NW)." (PMID 32397375, 2020). "The group (MD−/NW) was characterized with lower levels of CRP, leptin, MDA, and higher levels of sFasL, when compared to OW patients with PCOS in the absence of metabolic disorders (MD−/OW) (p < 0.05)." (PMID 32397375, 2020).
cardiovascular disease (295 papers, 2006 to 2026). "This link between ACEs and cardiovascular disease is supported by clear molecular mechanisms—dysregulated endothelin-1 and leptin are both associated with both ACEs and cardiovascular disease." (PMID 38384900, 2024). "The published analyses within the field employ a predominantly cross-sectional approach, neglecting the established and direct correlation between leptin and adipose mass, or leptin and increased risk of cardiovascular diseases (as extensively documented)." (PMID 38396763, 2024). "Multiple studies have described higher leptin levels as a risk factor for cardiovascular disease in the general population and in RA patients with a positive correlation with BMI." (PMID 39012360, 2024). "In consequence, leptin is used as a biomarker of systemic inflammation and cardiovascular disease (CVD) risk." (PMID 38668349, 2024). "Adiponectin and leptin, known for their anti-inflammatory and proinflammatory properties, respectively, have been implicated in cardiovascular diseases, but their associations with FCAVD are controversial." (PMID 39335491, 2024). "In contrast, leptin has been shown to have proinflammatory properties, and increased circulating leptin levels were associated with cardiovascular disease and adverse outcomes." (PMID 39335491, 2024). "Studies have demonstrated that fasting during Ramadan has been shown to increase HDL cholesterol, leptin, adiponectin, and insulin sensitivity, as well as lower several hemostatic risk factors for cardiovascular diseases." (PMID 38169925, 2023). "Elevated leptin levels, above 10 ng/L, have been linked to a notable increase in the risk of cardiovascular disease." (PMID 38111655, 2023). "Leptin increases the risk of cardiovascular disease, the most common cause of mortality in CKD patients." (PMID 36726470, 2022). "The inflammation caused by leptin stimulates vascular inflammation and eventually leads to cardiovascular disease." (PMID 36698957, 2022). "Leptin is an adipose tissue-derived endocrine factor that has been associated with several metabolic factors involved in cardiovascular diseases." (PMID 35619087, 2022). "In the evaluation of 818 elderly Framingham Study participants, leptin level was strongly associated with the incidence of congestive heart failure and cardiovascular disease." (PMID 35056647, 2022). "Polymorphisms of leptin and leptin receptor genes were also associated with the risk of cardiovascular disease in European and Asian populations." (PMID 33925217, 2021). "It was shown that low levels of adiponectin, increased concentration of leptin, and leptin resistance correlate with high risk of developing metabolic and cardiovascular disorders." (PMID 33536069, 2021). "Studies have reported that increased LAR is strongly associated with MetS and cardiovascular diseases than isolated leptin or isolated adiponectin concentrations." (PMID 34844584, 2021). "Significant differences were obtained in the adiponectin–leptin ratio (A/L ratio) of the entire sample (p = 0.009, ES = 0.53), which indicates a decrease in the risk of cardiovascular diseases and lipoinflammation." (PMID 32854366, 2020). "The purpose of this review is to discuss the mechanisms associated with leptin signaling deficiency or leptin resistance in the development of metabolic and cardiovascular diseases." (PMID 32655492, 2020). "It has been shown that leptin can increase the risk of CAD more than other risk factors for cardiovascular diseases such as sex, race, smoking, and body mass index." (PMID 33148166, 2020). "Climacterium is associated with elevated leptin levels and increased risk of cardiovascular disorders." (PMID 32555994, 2020). "This is supported by several studies, which showed that a higher leptin concentration was associated with increased risk for cardiovascular diseases." (PMID 30641979, 2019).
cardiovascular disease (continued). "Elevated circulating hsCRP and pro-inflammatory adipocytokines like FABP4, leptin and lipocalin-2 increase the risk for cardiovascular disease by not only endocrine but also paracrine mechanisms." (PMID 30395653, 2018). "The leptin/adiponectin (L/A) ratio is associated with cardiovascular disease and reflects adipose tissue dysfunction." (PMID 28077136, 2017). "Romero‐Corral and colleagues 21 stated that such interaction occurs when assessing cardiovascular disease, resulting in a weaker association between CRP and cardiovascular disease after adjustment for leptin." (PMID 26632325, 2016). "The primary objective of the present study is to explore the associations between serum leptin and all-cause mortality and mortality from cardiovascular disease (CVD) over a span of 10 years, controlling for body adiposity and proinflammatory cytokines." (PMID 26473487, 2015). "Studies on ADPN and the ADPN/LEP ratio as a valuable complementary diagnostic element in the prediction and prevention of cardiovascular diseases need to be continued." (PMID 26389928, 2015). "Some studies found positive associations between elevated serum leptin and the risk factors for cardiovascular disease among healthy and diabetic individuals." (PMID 26473487, 2015). "Adiponectin and leptin, two of the key cytokines secreted by adipocytes, have been shown to be associated with cardiovascular disease." (PMID 25793395, 2015). "Our findings suggest that leptin exerts its positive and vasodilator effect on endothelial function in overweight diabetic patients with an elevated risk for cardiovascular diseases." (PMID 24410779, 2014). "Obviously, leptin as a biomarker for body fat reflects a yet unexplored activity of adipocytes and can provide important information regarding the risk of cardiovascular disease." (PMID 24981337, 2014). "They concluded that leptin profile is possibly associated with the elevated incidence of cardiovascular diseases observed in the late post-transplant period." (PMID 25340128, 2013). "The adiponectin/leptin ratio also was shown to decrease with the increasing number of metabolic risk factors for cardiovascular disease." (PMID 23533722, 2013). "In a previous report, we observed that leptin levels were associated with cardiovascular disease risk factors." (PMID 22533665, 2012). "Leptin is associated with cardiovascular diseases (CVD), In fact, elevated serum concentrations of this adipokine are related with myocardial infarction and stroke independently of traditional cardiovascular risk factors." (PMID 22910888, 2012). "Leptin and adiponectin are two adipose tissue hormones and their association with the incidence of cardiovascular diseases is under evaluation." (PMID 22577414, 2010). "Notably, EPAC1 activators help reduce the risk of cardiovascular diseases by decreasing body weight and improving leptin sensitivity." (PMID 41503874, 2026). "Leptin is defined as pro-atherogenic, which corresponds with its association with a higher risk of cerebral vascular disease, carotid intimal hyperplasia, and cardiovascular disease." (PMID 41295840, 2025). "Integrating leptin measurements into cardiovascular risk calculators may therefore enhance the early detection and prevention of cardiovascular disease." (PMID 41470134, 2025). "Studies have demonstrated that leptin levels are elevated in the subcutaneous adipose tissue of prediabetic individuals, where it promotes inflammatory responses and increases the risk of cardiovascular diseases." (PMID 40242450, 2025). "It has been suggested that the L/A ratio may be a better indicator of the risk of lethal cardiovascular disease, as it wholly considers the synergistic relationship of pro-atherogenic leptin and anti-atherogenic adiponectin within the context of one another." (PMID 41295840, 2025).
cardiovascular disease (continued). "For example, a sedentary routine has been described to induce resistin and leptin as well as reduced plasma levels of adiponectin, which may promote cardiovascular disease, while regular exercise can mitigate such adipokine risk response." (PMID 39861386, 2025). "High levels of leptin, or hyperleptinemia, may increase the risk of cardiovascular diseases and contribute to the hardening of arteries due to its role in promoting the transformation of cells, which leads to vascular calcification." (PMID 39335491, 2024). "In addition, serum leptin was associated with markers of increased cardiovascular disease risk, especially in the NW mothers." (PMID 38668349, 2024). "Serum leptin levels have been shown to be associated with cardiovascular disease." (PMID 38111655, 2023). "Interestingly, the high levels of leptin and leptin resistance have been linked to the development of cardiovascular disease." (PMID 33495937, 2022). "Leptin is an adipose tissue-derived endocrine factor that has been associated with several metabolic, inflammatory, and hemostatic factors involved in the development of hypertension and cardiovascular diseases." (PMID 35619087, 2022). "In addition, elevated leptin levels have been shown to be directly associated with systemic inflammation, immune-mediated disease, cerebrovascular and cardiovascular disease, and it can lead to the autonomic dysregulation." (PMID 35720911, 2022). "More research is needed to see whether the effect of exercise on leptin levels in obese girl children can reduce the risk of cardiovascular disease in adulthood." (PMID 35720911, 2022). "But more research is needed to confirm whether the effect of exercise on leptin levels in obese female children can reduce the risk of cardiovascular disease in adulthood." (PMID 35720911, 2022). "Leptin, an inflammatory cytokine produced by adipocytes, contributes to the modulation of metabolism, respiratory control, and inflammation, which are factors associated with cardiovascular disease." (PMID 36254000, 2022). "It has been reported that treatment with canagliflozin improves adipose tissue functions; modifies levels of serum leptin, adiponectin, and interleukin 6; and may favorably affect insulin sensitivity and other risk factors for cardiovascular disease." (PMID 35884961, 2022). "The present conclusions have clinical importance because an elevated leptin level could be a risk factor for the development of cardiovascular disease in adults with OSAS." (PMID 34671315, 2021). "Our study suggests that a small portion of the association between leptin and cardiovascular disease could be mediated via A-FABP, especially in men." (PMID 32753620, 2020). "In this regard, elevated leptin levels in obese patients are believed to contribute to the low-grade systemic inflammation, which makes obese individuals more susceptible to develop cardiovascular diseases." (PMID 32655492, 2020). "Elevated leptin levels are therefore considered a risk factor for cardiovascular disease." (PMID 30774721, 2019). "Indeed, several studies have shown strong associations between leptin, adiponectin, and cardiovascular disease." (PMID 31126896, 2019). "Furthermore, the Adpn/Lep ratio better predicts the risk of cardiovascular diseases, as compared to the individual leptin and adiponectin concentrations." (PMID 31484347, 2019). "Moreover, increased plasma levels of leptin are independently associated with serum C-reactive protein concentrations, an acute marker of inflammation and a direct cause of cardiovascular diseases." (PMID 31500090, 2019). "Adiponectin and leptin are well known to play important roles in regulating metabolic homeostasis and are linked to several pathophysiological conditions and diseases including cardiovascular disease (CVD)." (PMID 31703113, 2019).